GABRD (gamma-aminobutyric acid type A receptor subunit delta)
Diseases named in the same sentence as GABRD in open-access papers (continued):
Sharing a sentence is not in itself a finding about the gene and the disease.
gastric cancer (4 papers, 2023 to 2026). A primary or metastatic malignant neoplasm involving the stomach. "We then evaluated the potential associations between GABRD expression and clinicopathological characteristics of gastric cancer patients." (PMID 40145254, 2025). "Additionally, GABRD overexpression in our study was significantly associated with advanced tumour features such as lymph node metastasis and higher T‐stage, indicating an association between GABRD levels and the metastatic potential of gastric cancers." (PMID 40145254, 2025). "Additional IHC analysis confirmed a significant association between GABRD and CCND1 protein expressions in gastric cancer tissues (p = 0.00917)." (PMID 40145254, 2025). "Together, these data further suggested that GABRD significantly promotes gastric cancer cell tumorigenesis and growth in vivo." (PMID 40145254, 2025). "Then, we performed immunohistochemical (IHC) analysis to detect GABRD protein expression on the tissue micro‐array of 86 pairs of gastric adenocarcinoma tissues and normal gastric tissues plus 8 gastric cancer tissues (HStmA180Su19)." (PMID 40145254, 2025). "Then, the effect of GABRD on gastric cancer cell migration and invasion was estimated by transwell migration and wound‐healing assays." (PMID 40145254, 2025). "Overall, these findings uncover a role for the neurotransmitter receptor GABRD in regulating the proliferation and apoptosis of gastric cancer cells." (PMID 40145254, 2025). "While our work lays a foundation for understanding the clinical and molecular significance of GABRD in gastric cancer, it also opens several avenues for future research." (PMID 40145254, 2025). "To explore the potential roles of GABRD in the carcinogenesis of gastric cancer, we first analysed the GABRD mRNA expression levels in 375 stomach adenocarcinoma tissues and 32 normal tissues from the TCGA database." (PMID 40145254, 2025). "GABRD was knocked down by small hairpin RNA (shRNA) targeting GABRD to explore the potential role of GABRD in gastric cancer cells." (PMID 40145254, 2025). "Our investigation revealed significant GABRD overexpression in both gastric cancer tissues and cell lines, aligning with analyses from the TCGA‐Stomach Adenocarcinoma (TCGA‐STAD) dataset." (PMID 40145254, 2025). "Our findings identify GABRD as a novel oncogene in gastric cancer, promoting malignant phenotypes through CCND1‐dependent cell cycle regulation." (PMID 40145254, 2025). "Taken together, our study identifies GABRD as a potential oncogene in gastric cancer, promoting tumour progression and affecting patient survival outcomes." (PMID 40145254, 2025). "After evaluating GABRD expression in gastric cancer and normal cell lines, AGS and MGC‐803 cells were chosen for further investigation due to their higher and stable GABRD levels." (PMID 40145254, 2025). "It is conceivable that dynamic trafficking or compartmentalisation of GABRD contributes to its oncogenic function in gastric cancer." (PMID 40145254, 2025). "These sample constraints underscore the need for larger, more detailed studies to fully evaluate the role of GABRD expression across the full clinical spectrum of gastric cancer." (PMID 40145254, 2025). "The crucial involvement of GABRD in gastric cancer progression led us to explore GABRD‐regulated genes." (PMID 40145254, 2025). "The Celigo Cell Counting assay showed GABRD knockdown markedly impeded proliferation in gastric cancer cells." (PMID 40145254, 2025). "The results indicated that GABRD protein was over‐expressed in gastric cancer samples versus normal samples, with high GABRD in 49% of cancerous tissues versus 3.5% in adjacent para‐carcinoma tissues." (PMID 40145254, 2025). "In this study, we first identified GABRD as a novel oncogene in gastric cancer and investigated its molecular mechanism in gastric cancer." (PMID 40145254, 2025).
gastric cancer (continued). "The growth of gastric cancer cells was suppressed in vitro by anti-GABRD polyclonal antibodies, which also led to a reduction in the size of peritoneal tumor nodules in the mouse xenograft model." (PMID 37181811, 2023). "To date, the functional roles of GABRD in gastric cancer remain largely unexplored." (PMID 40145254, 2025). "By situating GABRD within the growing field of neurotransmitter‐driven oncogenesis, we provide foundational evidence for further mechanistic investigations, including possible electrophysiological and microenvironmental interventions in gastric cancer." (PMID 40145254, 2025). "Results of in vivo bioluminescence imaging, indicative of tumour size, showed that down‐regulation of the expression of GABRD could inhibit the development of gastric cancer in mice." (PMID 40145254, 2025). "It has been suggested that GABRD may be a viable therapeutic target for gastric cancer since its expression is increased in gastric cancer tissue and it is related to a poor prognosis." (PMID 37181811, 2023). "Next, to examine the effect of GABRD on cell apoptosis, Annexin V‐APC staining showed that the percentage of apoptotic gastric cancer cells was remarkably elevated in the shGABRD group than in the shCtrl group." (PMID 40145254, 2025). "Recent investigations have revealed aberrant expression of GABRD across a spectrum of non-neural malignancies, including breast, colorectal, and gastric cancers, wherein it exhibits a multifaceted and paradoxical role in oncogenesis." (PMID 41900986, 2026). "It is plausible that the GABRD's function in gastric cancer may not be limited to intracellular protein–protein interactions but could also involve ion channel activity influencing membrane potentials or crosstalk with the tumour microenvironment." (PMID 40145254, 2025). "However, survival analysis revealed that GABRD and DDX10 did not exhibit significant differences in gastric cancer prognosis." (PMID 40444099, 2025).
generalized epilepsies (4 papers, 2020 to 2022). "Gamma-aminobutyric acid type A receptor subunit delta (GABRD) has been suggested as a susceptibility gene to childhood-onset mood disorders and generalized epilepsies." (PMID 35706026, 2022). "Furthermore, we identified six patients with GOF GABRD variants that shared common phenotypes of neurodevelopmental disorders with generalized epilepsy, behavioural issues, and various degrees of intellectual disability." (PMID 35383156, 2022). "Previous studies have shown that mutations of the GABA receptors, such as, GABRA1, GABRA5, GABRA6, GABRB3, GABRD, GABRG2, were associated with idiopathic generalized epilepsy." (PMID 35663265, 2022). "Gamma-aminobutyric acid type A receptor subunit delta (GABRD), which encodes the GABAA receptor δ subunit, has been suggested as a susceptibility gene to childhood-onset mood disorders and generalized epilepsies." (PMID 33336074, 2020).
juvenile myoclonic epilepsy (4 papers, 2018 to 2024). "GABRD encodes the delta subunit of the gamma-aminobutyric acid A receptor and has been associated with juvenile myoclonic epilepsy." (PMID 29649218, 2018). "In 2018, Bhat and colleagues found that polymorphism in the GABRD gene, as well as other GABAA receptor genes, may be associated with juvenile myoclonic epilepsy and Lennox–Gastaut syndrome." (PMID 36369750, 2023). "In patients with juvenile myoclonic epilepsy, several individual loci are involved, of which GABRA1, GABRD, EFHC1, BRD2, CASR, and ICK with complex inheritance are considered to be the most pathogenic." (PMID 39513854, 2024).
depression (2 papers, 2022 to 2025). "A pilot study examining the GABAergic system in suicide victims found GABRD variants in the prefrontal cortex of patients associated with depressive disorder." (PMID 35806070, 2022).
hepatocellular carcinoma (2 papers, 2023 to 2024). A malignant tumor that arises from hepatocytes. "CDH13 was notably a top upregulated gene obtained from the linear modeling of hepatocellular carcinoma (only after GABRD and PLVAP) in an earlier analysis; these observations point to a consistent role for members of the cadherin gene family in cancer progression in gastrointestinal cancers." (PMID 39484215, 2024). "It is significant that GABRD emerges as a stage-IV salient gene in COADREAD, reinforcing its identification as a stage-IV salient gene in hepatocellular carcinoma, and suggesting a driver role in the metastasis of gastrointestinal cancers more generally." (PMID 39484215, 2024).
heroin addiction (2 papers, 2020 to 2022). "A recent report showed a marginal association between GABRD haplotype and heroin dependence in 446 patients and 400 controls." (PMID 36614162, 2022). "Furthermore, epigenetic regulation through DNA methylation of GABRD may be the main regulatory mechanism underlying heroin addiction and responsible for the neuroadaptations induced by heroin." (PMID 33551813, 2020). "Collectively, these results suggest that targeting the GABRD gene and its methylation might represent a novel pharmacological strategy for treating heroin addiction and relapse." (PMID 33551813, 2020). "In summary, the present results demonstrated that GABRD might be a potential biomarker and drug target for heroin addiction and relapse." (PMID 33551813, 2020). "However, the methylation of GABRD in heroin addiction is rarely mentioned." (PMID 33551813, 2020). "However, no study has reported a correlation between GABRD methylation and heroin addiction." (PMID 33551813, 2020).
Nicotine addiction (2 papers, 2022). "Several switch genes, including GABRA1 and GABRD, were linked to nicotine addiction in M-AD." (PMID 36389068, 2022).
amyloidosis (1 paper, 2023). A disorder characterized by the localized or diffuse accumulation of amyloid protein in various anatomic sites. "It is possible that certain wake-promoting neuron groups possess GABRD and, if impacted by amyloidosis or astrogliopathy, they may promote sleep and have important implications on our understanding of the hierarchy within sleep–wake neurocircuitry." (PMID 37298646, 2023).
COVID-19 (1 paper, 2022). A disease caused by infection with severe acute respiratory syndrome coronavirus 2. "Using network pharmacology, we identified 7 core targets of curcumol against COVID-19 and COAD, including GABRD, GABRP, BCHE, CYP3A4, PGR, HSD17B2, and SLC6A3." (PMID 35967794, 2022). "So, the GABAA receptor subtypes GABRD and GABRP might be the promising targets of curcumol for treating COAD and COVID-19." (PMID 35967794, 2022).
dementia (1 paper, 2024). Loss of intellectual abilities interfering with an individual's social and occupational functions. "Therefore, the decrease in GABRD+ or GPR162+ carrying pTau217 EVs may simply be due to neuronal loss as dementia progresses, although other mechanisms require further investigation." (PMID 38444036, 2024).
fragile X syndrome (1 paper, 2014). A genetic syndrome caused by mutations in the FMR1 gene which is responsible for the expression of the fragile X mental retardation 1 protein.
lung adenocarcinoma (1 paper, 2014). A carcinoma that arises from the lung and is characterized by the presence of malignant glandular epithelial cells. "We identified alterations in genes involved in chromatin remodeling (PBRM1, SETD2), oxidative stress (CUL3, SOD2), immune response (CSMD3, SYK), and gamma-aminobutyric acid receptor signaling (GABRD, GABRG1) in lung adenocarcinoma." (PMID 24576404, 2014).
metastatic tumor (1 paper, 2022). "In addition, the higher expression of GABRD was correlated with the later stage, metastatic tumor, and a higher number of tumors spread to the lymph nodes in COAD." (PMID 35967794, 2022).
neuropathy (1 paper, 2022). A disorder affecting the nervous system that manifests with pain, tingling, numbness, and/or muscle weakness. "Specifically, these DEGs were associated with neuropathy-related pathways, such as GABRD, GABRP, TBX1, and SOX10, and inflammatory responses such as CXCL3, CXCL12, TNF, and IL6." (PMID 36147849, 2022).
Obesity (1 paper, 2021). Accumulation of substantial excess body fat. "The results revealed that 18 of the DMR genes were associated with addiction and obesity (ADCY3; ADCY9; ATF4; CDK5R1; CHRNB2; GABRD; GABRG3; GNB1; GNB3; GRK5; HDAC4; HDAC9; MAP2K1; PDE11A; PDE2A; PDE3A; PPP1CA; SLC6A3)." (PMID 34389046, 2021).
prion disease (1 paper, 2023). A transmissible disease that is caused by a protein that is able to induce abnormal folding of normal cellular proteins, leading to characteristic spongiform brain changes, which are associated with neuronal loss without an inflammatory response. "The expression of GABRD was significantly associated with pathways related to glycine, serine, and threonine metabolism, glycosaminoglycan biosynthesis (chondroitin sulfate), olfactory transduction, phenylalanine metabolism, prion diseases, and SNARE interactions in vesicular transport." (PMID 38099288, 2023).
renal cell carcinoma (1 paper, 2015). "We observed a particularly large effect in renal cell carcinoma where there is a ten-fold median decrease in GABRA2 alongside a six-fold increase in expression of GABRD." (PMID 26555223, 2015).
temporal lobe epilepsy (1 paper, 2024). A localization-related (focal) form of epilepsy characterized by recurrent seizures that arise from foci within the temporal lobe, most commonly from its mesial aspect. "Limited to patients with temporal lobe epilepsy, we detected a significant correlation between the exponent and the cortical expression of GABRA1, GRIN2A, GABRD, GABRG2, KCNA2 and PDYN genes." (PMID 39056027, 2024).
tumor (18 papers, 2014 to 2026). "In the multivariate analysis using a Cox proportional hazards model, GABRD overexpression was significantly and independently associated with shorter OS, after adjustment by age, tumor size, and tumor stage." (PMID 33336074, 2020). "However, GABRD expression was significantly decreased in IDH wild‐type diffuse low‐grade gliomas (LGG) compared with that in IDH mutant tumours and was independently associated with longer OS in IDH WT LGG." (PMID 40145254, 2025). "The tumour tissues exhibited significantly higher GABRD mRNA expression levels than the normal tissues." (PMID 40145254, 2025). "GABRD knockdown significantly suppresses tumour proliferation and migration in vitro and in vivo, and its upregulation correlates with advanced tumour stage and unfavourable prognosis." (PMID 40145254, 2025). "Pan‐cancer analysis of over 600 tumour and adjacent normal tissue pairs from The Cancer Genome Atlas (TCGA) revealed significant GABRD overexpression in 89% of subjects." (PMID 40145254, 2025). "Intriguingly, analyses of TCGA data reveal that GABRD, encoding a GABA receptor subunit, is often upregulated in tumours compared to adjacent normal tissues." (PMID 40145254, 2025). "This lack of expression is unlikely to be due to the differences between scRNA-seq and snRNA-seq because the one MBEN tumor in our cohort with scRNA-seq data clearly shows a group of GABRD + /VSNL1+ cells." (PMID 38191555, 2024). "Their impact on the prevalence of specific immune cell types suggests the role of immunosuppressive factors such as UCN and GABRD in tumor-promoting properties, presenting valuable targets for therapeutic intervention." (PMID 39336730, 2024). "The CHRNA3, GABRD, GRIK3 and GRIK5 gene are associated with the sensitivity of certain anti-tumor drugs such as fluphenazine, pimozide, isotretinoin, and fludarabine." (PMID 38099288, 2023). "Results revealed that, compared to normal tissues, the expression of CHRNA3, GRIK3, and GRIK5 is decreased in tumor tissues, while GABRD is highly expressed in tumor tissues, consistent with our bioinformatics analysis results." (PMID 38099288, 2023). "In the GSEA, a high expression of GABRD was positively correlated to several gene sets that are closely related to carcinogenesis and tumor progression, including EMT, angiogenesis, hedgehog signaling, KRAS signaling, Wnt-β-catenin signaling, and UV response." (PMID 33336074, 2020). "Common to both analyzed cohorts was the underexpression of GABBR1, and the overexpression of GABRD, in tumor vs normal tissues." (PMID 33187258, 2020). "Overexpression of GABRD accelerated tumor cell proliferation and migration, while silencing of GABRD yielded the opposite effects." (PMID 33336074, 2020). "Knockdown of GABRD resulted in a decrease in the mean weight of tumours." (PMID 40145254, 2025). "Clinical evaluations of GABRD and its downstream effectors may eventually enable precision therapies that target the aberrant GABAergic circuitry in the tumour milieu." (PMID 40145254, 2025). "Knockdown of GABRD could markedly induce cell apoptosis and cell cycle arrest while repressing proliferation and migration in vitro, and suppress tumour growth in vivo." (PMID 40145254, 2025). "GABRD expression was negatively correlated with the extent of tumor infiltration by macrophages." (PMID 38539663, 2024). "Both immunohistochemistry and RT-PCR confirmed the high expression of GABRD in tumor tissues." (PMID 38099288, 2023). "In colorectal cancer, GABRD has been hypothesized to have a role similar to that of a tumor promoter in a previous study." (PMID 37181811, 2023). "The signal intensity of GABRD in tumor tissue is stronger than that in normal tissue." (PMID 35706026, 2022). "Third, as clinical evidence suggested that GABRD might have influence more on tumor carcinogenesis than on metastasis, while in vitro experiments indicated that it promoted tumor proliferation and migration." (PMID 33336074, 2020).